Y_RNA (Y RNA )
Gene: Miscellaneous RNA gene on chromosome 7 (67,297,653 to 67,297,754, reverse strand). Ensembl gene ENSG00000201565.
Homologues: Orthologues: chimpanzee Y_RNA (100% identical), pig Y_RNA (73% identical). Paralogues in human: Y_RNA (100% identical), Y_RNA (99% identical), Y_RNA (93% identical), Y_RNA (90% identical), RNY3 (89% identical), RNY3P1 (88% identical), Y_RNA (87% identical), Y_RNA (86% identical), Y_RNA (85% identical), Y_RNA (84% identical), RNY3P13 (83% identical), RNY3P14 (83% identical), and 98 more.